RNU2-5P (RNA, U2 small nuclear 5, pseudogene)
Synonyms: U2; u2.7; RNU2P3
Gene: Small nuclear RNA gene on chromosome 9 (70,188,571 to 70,188,750, reverse strand). Ensembl gene ENSG00000222465.
Homologues: Orthologues: chimpanzee U2 (98% identical), macaque U2 (97% identical). Paralogues in human: U2 (91% identical), RNU2-4P (89% identical), RNU2-2 (87% identical), RNU2-52P (87% identical), U2 (87% identical), RNU2-3P (86% identical), RNU2-48P (86% identical), RNU2-26P (84% identical), RNU2-17P (84% identical), RNU2-57P (84% identical), RNU2-59P (84% identical), RNU2-6P (84% identical), and 67 more.